BARD1 (BRCA1 associated RING domain 1)
Diseases named in the same sentence as BARD1 in open-access papers (continued):
Sharing a sentence is not in itself a finding about the gene and the disease.
ovarian carcinoma (continued). "Pathogenic variants in PALB2, ATM and BARD1 are recognized by the NCCN as involved in hereditary breast and ovarian cancer syndrome but have insufficient evidence to determine their ovarian cancer risk." (PMID 35159349, 2022). "The advancement of technology revealed the critical role of many genes, such as BRCA1/2 and BARD1, in hereditary and familial breast and ovarian cancers." (PMID 35650591, 2022). "A mutational analysis study was conducted among 126 Finnish breast and/or ovarian cancers families to investigate the potential contribution of BARD1 alterations to tumor development." (PMID 35650591, 2022). "This probability was further increased in patients presented with double mutations of BARD1 Cys557Ser joint with XRCC3 241Met variant (P = 0.02, OR = 5.01 [95% CI 1.36–18.5]) among patients with a family history of breast or/an ovarian cancer." (PMID 35650591, 2022). "We were unable to identify mutations in EMSY, BRIP, BARD1, and FOXM1 CNV in high-grade ovarian carcinoma as well as PTEN loss in clear cell carcinoma, LRPB1 loss and SOX17 amplification in uterine serous carcinoma." (PMID 36010253, 2022). "Here, in a study of a hereditary breast and ovarian cancer susceptible (HBOC) family, we find that two BARD1 mutations (P24S and R378S) simultaneously exist in surviving cancer patients." (PMID 33623049, 2021). "In our case-control analyses with a non-cancer east-Asian population and non-cancer females, we found significant prevalence of PALB2, BARD1, BLM, and ATM mutations in our HBOC cohort, including patients with ovarian cancer." (PMID 32566746, 2020). "In this study, we aim to gain insight in the germline mutation spectrum of ATM, BARD1, BRIP1, ERCC4, PALB2, RAD51C and RAD51D in breast and ovarian cancer families from Spain." (PMID 32756499, 2020). "Breast cancer gene 1 (BRCA1)-associated RING domain protein 1 (BARD1) forms a heterodimer with BRCA1, a tumor suppressor associated with hereditary breast and ovarian cancer." (PMID 32722046, 2020). "The results of this study reveal functional domains of BARD1 and suggest that the functional analysis of BARD1 HDR activity is predictive of breast and ovarian cancer risk." (PMID 30925164, 2019). "The BARD1 gene (MIM# 601593) was identified in 1996 as the result of a yeast two-hybrid screen for proteins that interact with the breast and ovarian cancer associated BRCA1 protein." (PMID 31803232, 2019). "We applied the Lasso fitted 27-antigen model on test results for sera from breast and ovarian cancer and neuroblastoma patients to determine the BARD1 lung cancer test specificity in respect of possible cross-reactivity with other cancers." (PMID 28786985, 2017). "We also expect that massive sequencing of BARD1 in breast, ovarian cancers, neuroblastoma and other tumors will increase the number of rare pathogenic missense mutations to be inserted into the ClinVar database as “Pathogenic”." (PMID 29292755, 2017). "In breast and ovarian cancer an imbalance of FL BARD1 and BARD1β was observed with BARD1β dominant negative function." (PMID 29292755, 2017). "To further elucidate the role of large mutations in BARD1, we designed a multiplex ligation-dependent probe amplification (MLPA) assay and performed an analysis of 504 women with a familial breast and/or ovarian cancer and 313 patients with ovarian cancer." (PMID 25994375, 2015). "Proteins MSLN and BARD1 are well-known autoantigens of ovarian cancer and have also been found by SEREX." (PMID 18173842, 2008). "Only one BARD1 carrier had multiple cancers, including ovarian cancer and cancer of the uterus." (PMID 40805222, 2025).
ovarian carcinoma (continued). "The associations of age at ovarian cancer diagnosis and histology between BARD1 mutation carriers and BRCA1/2 mutation carriers were not calculated due to limited case numbers." (PMID 40805222, 2025). "Further, mutations in BRCA1 pose high risk for both breast and ovarian cancer, while BARD1 mutations are only a risk factor for breast, but not ovarian cancer." (PMID 36716349, 2023). "Interestingly, germline mutations in PALB2 and BARD1 and a high HRD score were identified in NETs, a rare tumor among malignant ovarian tumors." (PMID 35676859, 2023). "Other U.S. cohorts compared to the same controls have not found BARD1 to be significantly associated with ovarian carcinoma." (PMID 35159349, 2022). "Germline BARD1 variants appear to convey a low-moderate risk of ovarian cancer, but do not appear to explain non-BRCA1/2 breast and ovarian cancer heritability." (PMID 34680387, 2021). "BARD1 expression in breast and ovarian cancer also shows positive correlations with poor prognosis." (PMID 32719318, 2020). "The BARD1 and NBN genes were included in breast/ovarian cancer genetic panel tests, due to their breast cancer risk, despite the ovarian cancer risk for deleterious variants in these genes being unknown." (PMID 33086730, 2020). "We aimed to assess the role of deleterious BARD1 germline variants in BC/OC predisposition in a sample of 4920 BRCA1/2-negative female BC/OC index patients of the German Consortium for Hereditary Breast and Ovarian Cancer (GC-HBOC)." (PMID 31036035, 2019). "BARD1 protein is encoded by sequences on chromosome 2q35 and forms a functional heterodimer with BRCA1 through the binding of their RING-finger domains which functions as tumor-suppressor in breast and ovarian cancer." (PMID 29292755, 2017). "BARD1 gene mutations affect the function of the BRCA1/BARD1 heterodimer, which may affect cancer progression, particularly in breast and ovarian cancer." (PMID 28794477, 2017). "A sequencing of 20 complete genes, including noncoding and flanking sequences, in hereditary breast and ovarian cancer patients (n = 287) identified a single nucleotide variants in 5’ UTR (c.-53G > T; rs143914387) of BARD1 predicted to alter the mRNA structure." (PMID 29292755, 2017). "Furthermore, BARD1 isoforms have been described in particular in breast and ovarian cancers, as well as neuroblastoma, although with a cancer-type specific pattern of expression." (PMID 28786985, 2017). "In conclusion, although we cannot exclude the presence of large mutations in BARD1, our study indicates that such mutations do not contribute substantially to the risk of breast and/or ovarian cancer." (PMID 25994375, 2015). "BARD1 has been previously characterised as an important contributor to breast and ovarian cancer." (PMID 24454733, 2014). "Over the past years BARD1 (BRCA1-associated RING domain 1) has been considered as both a BRCA1 (BReast Cancer susceptibility gene 1, early onset) interactor and tumor suppressor gene mutated in breast and ovarian cancers." (PMID 24349422, 2013). "Many mutations have been identified in BARD1 in non-hereditary site-specific breast and breast/ovarian cancer cases." (PMID 23056176, 2012). "The Cys557Ser missense variant was identified within the BARD1 region that was required to regulate apoptosis and transcriptional machinery and revealed higher frequency in the breast, but not ovarian cancer cases compared to healthy controls (7.4 vs 1.4%, p = 0.001)." (PMID 35650591, 2022). "CA125 showed higher sensitivity than the BARD1 261-sample-fitted model for OC with or without BRCA1/2 or BARD1 mutations, presumably this reflects that those sub-groups contained more late-stage ovarian cancers, which are better detected by CA125 than early-stage cancers." (PMID 34201956, 2021).
ovarian carcinoma (continued). "Ratajska and colleagues screened 109 BRCA1/2 negative high-risk breast and/or ovarian cancer patients from North-Eastern Poland for BARD1 germline mutations and identified three different BARD1 variants suspected to be pathogenic (c.1690C>T, p.Gln564X; c.1315- 2A>G; c.1977A>G)." (PMID 26075229, 2015). "However, the association of BARD1 with ovarian cancer has not been convincingly established." (PMID 40805222, 2025). "Abnormal BARD1 isoforms have been detected in non-small cell lung cancer (NSCLC), as well as in breast, colon, and ovarian cancers." (PMID 40805222, 2025). "However, unlike the BRCA1 and BRCA2 genes, which have clustered regions associated with breast and ovarian cancers, no clear hotspot could be identified in BARD1." (PMID 40805222, 2025). "BRCA1, a tumor suppressor protein of breast and ovarian cancer, binds to a RING finger protein BARD1 to form a ring heterodimer and it functions as an E3 ubiquitin ligase for ubiquitination." (PMID 35265070, 2022). "Abnormal BARD1 isoforms are found in non-small cell lung cancer (NSCLC), breast, colon, and ovarian cancers delivering a role in cancer tumorigenesis and progression." (PMID 35650591, 2022). "Structurally, BARD1 has homologous domains to BRCA1 that aid their heterodimer interaction to inhibit the progression of different cancers such as breast and ovarian cancers following the BRCA1-dependant pathway." (PMID 35650591, 2022). "BARD1, as a BRCA1 heterodimer interactor that plays an essential role as a tumor suppressor gene altered in breast and ovarian cancers, was also found to display a BRCA1-independent function during cancer progression." (PMID 35650591, 2022). "For example, the BARD1 and NBN (miR-548ai targets), BRIP1 (miR-567 target), and CHEK2 (miR-943 target) genes, which are known to be involved in breast and ovarian cancers." (PMID 34768979, 2021). "The breast and ovarian cancer-specific tumor suppressor BRCA1, along with its heterodimer partner BARD1, plays a critical role in DNA repair, drug resistance, centrosome regulation, and transcription." (PMID 32528278, 2020). "The protein product of the breast and ovarian cancer gene, BRCA1, is part of an obligate heterodimer with BARD1." (PMID 28032817, 2017). "Notably, BARD1 shares a structurally homologous domain with BRCA1, and these two proteins interact to impede the progression of different cancers, including breast and ovarian cancers, through the BRCA1-dependent pathway." (PMID 37727789, 2023). "Other mutations were uniquely enriched in HRD+ predicted cases of breast and ovarian cancers (BARD1, BRIP1, MRE11, RAD51D) and cancer cohorts outside breast and ovarian cancer (RAD51B), suggesting additional unique drivers of HRD that may be cancer-cohort specific." (PMID 35643464, 2022). "The BARD1 antibody test is highly specific for lung cancer and not breast or ovarian cancer." (PMID 28786985, 2017). "Interestingly for ovarian cancer, it has been shown to interact with the BRCA1/BARD1 complex." (PMID 20386695, 2010).
neuroblastoma (45 papers, 2012 to 2025). Neuroblastoma (NB) is the most common solid, extracranial childhood tumor. "Beyond rare pathogenic mutations, single-nucleotide polymorphisms (SNPs) in BARD1 have also emerged as important regulators of cancer susceptibility, particularly highlighted in neuroblastoma, nephroblastoma, and gynecologic malignancies." (PMID 41009605, 2025). "For neuroblastoma patients with LoF BARD1 variants, PARP inhibition has been shown to be an effective therapy." (PMID 41282735, 2025). "Germline PVs in BARD1 have been implicated in increased risk for early-onset BC, especially triple negative, neuroblastoma, and mesothelioma." (PMID 40649708, 2025). "BARD1 variants have been also linked to hereditary breast cancer and more recently neuroblastoma through case-control studies." (PMID 41282735, 2025). "Among a cohort of 222 patients diagnosed with aggressive neuroblastoma, two germline BARD1-truncating variants were identified." (PMID 38397209, 2024). "This discovery prompts an inquiry into the potential involvement of BARD1 variants in the context of high-risk neuroblastoma." (PMID 38397209, 2024). "The genome-wide association study (GWAS) associated several BARD1 variants with susceptibility to high-risk neuroblastoma, mainly rs6435862 T>G was related with overexpression of BARD1 β." (PMID 33530592, 2021). "Genome-wide association studies (GWAS) identified common variations at the BARD1 locus to be highly associated with aggressiveness of high-risk neuroblastoma." (PMID 34884690, 2021). "Conversely, SNPs associated with decreased BARD1-FL expression were associated with higher-risk neuroblastoma." (PMID 33672422, 2021). "Common variants in BARD1 have also been related to a genetic susceptibility to neuroblastomas, colorectal and lung cancer but based on single reports." (PMID 34771627, 2021). "The role of BARD1 in limiting tumorigenesis has been highlighted in studies of neuroblastoma, where single nucleotide polymorphisms (SNPs), which increase full-length BARD1 mRNA (BARD1-FL) expression, hinder tumour progression." (PMID 33672422, 2021). "The expression of the full-length isoform of BARD1 has been demonstrated to prevent malignant transformation of NB cells, negatively correlated with high-risk neuroblastoma development." (PMID 34884690, 2021). "On the other hand, a subset of high‐risk neuroblastomas harbor increased expression of BARD1, a protein that complexes with BRCA1 to maintain genomic stability but also has oncogenic properties." (PMID 33480449, 2021). "Particularly, the expression of full length (FL) isoform, FL BARD1, correlates to high-risk neuroblastoma development and its inhibition is sufficient to induce neuroblastoma cells towards a worst phenotype." (PMID 32047556, 2020). "Another polymorphic locus that has been strongly associated with neuroblastoma and poor prognosis is BARD1 located at chromosome 2q35." (PMID 30760980, 2019). "Among the six relatively poor prognostic markers, ALK and BARD1 have been reported as neuroblastoma predisposition genes." (PMID 28984200, 2017). "BARD1β oncogenic driver of tumorigenesis is also supported by GWAS that identified BARD1 as new susceptibility locus in neuroblastoma." (PMID 29292755, 2017). "Single nucleotide polymorphisms (SNPs) in introns of BARD1 correlated with a subclass of highly aggressive and treatment resistant neuroblastoma and with elevated expression of the alternatively spliced BARD1β isoform." (PMID 28030839, 2017). "This was confirmed by the genome wide association study for neuroblastoma, where SNPs in intron 1 of BARD1 were the most significantly associated with the disease." (PMID 28030839, 2017).
neuroblastoma (continued). "Further evidence for a functional link between malignant transformation and alternatively spliced BARD1 isoforms came with the identification of BARD1 as a neuroblastoma predisposition gene in a genome wide association study." (PMID 28030839, 2017). "They show that common variation in BARD1 associates with the risk of the aggressive and most clinically corresponding subtype of human neuroblastoma." (PMID 28055978, 2017). "The reported SNPs at previously identified neuroblastoma susceptibility loci, including 2q35 (BARD1), 6p22.3 (CASC15), and 11p15.4 (LMO1) were also nominally associated with 11q deletion." (PMID 28924153, 2017). "We have demonstrated that, in BARD1 locus, SNPs associated with risk of neuroblastoma correlates with high expression of splice variants of BARD1 and SNPs protecting against neuroblastoma correlates with high expression of FL BARD1." (PMID 29292755, 2017). "BARD1 is a known neuroblastoma susceptibility locus but little is known about the frequencies of rare variants." (PMID 27009842, 2016). "Over the past years increasing evidence has emphasized the involvement of BARD1 (BRCA1-associated RING domain 1) in the pathogenesis of different cancers, including breast, ovarian, uterine, colon and lung cancer, as well as neuroblastoma." (PMID 24349422, 2013). "As a matter of fact, SNPs in BARD1 coding region cause the expression of an oncogenic isoform and that influence the neuroblastoma susceptibility and oncogenicity." (PMID 23056176, 2012). "Briefly, SNPs in BARD1 are among the most consistently identified neuroblastoma-susceptibility genes across multiple ethnic groups, although cancer susceptibility varies depending on the genomic context and the functional consequences of these variants on BARD1 mRNA expression." (PMID 41009605, 2025). "Furthermore, single-nucleotide polymorphisms associated with neuroblastoma risk, such as rs7585356, were shown to alter microRNA binding within the BARD1 3’ untranslated region (3’UTR), further linking genetic variation to isoform-specific expression control." (PMID 41009605, 2025). "BARD1 is associated with the development of high-risk neuroblastoma patients." (PMID 32047556, 2020). "Moreover, the association of these SNPs to neuroblastoma risk has also been replicated in many other populations, especially the SNPs in the BARD1 gene." (PMID 31583029, 2019). "However, different copy number variants of the BARD1 locus have been associated with congenital heart defects, aortic narrowing and tetralogy of Fallot all of which, as for neuroblastoma, have tissues that are derived from neural crest cells." (PMID 30760980, 2019). "GWAS identified SNPs within the BARD1 locus that is strongly associated with neuroblastoma." (PMID 30760980, 2019). "Moreover, others and we have demonstrated that BARD1 is enriched in rare, potentially pathogenic, germline variants also in neuroblastoma patients." (PMID 29292755, 2017). "Together, these evidences highlight that the risk of neuroblastoma development may be estimated by a specific combination of BARD1 risk genotypes as suggested by the results of a published computational analysis of GWAS-identified neuroblastoma risk loci." (PMID 29292755, 2017). "Furthermore, by performing a fine mapping analysis of BARD1 locus, we have identified additionally functional polymorphisms associated with risk of neuroblastoma and over-expression of FL BARD1." (PMID 29292755, 2017). "In that GWAS, one of the most significant and robustly replicated association signals that was enriched in the high-risk subset of neuroblastomas resided in the BARD1 locus that is also the only neuroblastoma susceptibility gene validated in Afro-American, Chinese and Spanish individuals." (PMID 29292755, 2017). "Indeed there is evidence that SNPs in BARD1 that are associated with a subgroup of high-risk, aggressive, neuroblastoma, promote alternative splicing and expression of BARD1β." (PMID 26415510, 2015).